PPM1G (protein phosphatase, Mg2+/Mn2+ dependent 1G)
Synonyms: PP2CG; PP2Cgamma; PPP2CG
Tractability: PROTAC: ubiquitination databases record sites on it; its protein half-life has been measured.
Target class: Protein Phosphatase; Phosphatase; Serine/threonine protein phosphatase; Enzyme
Gene: Protein-coding gene on chromosome 2 (27,381,194 to 27,409,674, reverse strand). Ensembl gene ENSG00000115241.
Subcellular location: Cytoplasm; Membrane
Subcellular location (Human Protein Atlas): Nucleoplasm
Gene Ontology:
Molecular function: protein binding; protein serine/threonine phosphatase activity; cation binding; phosphoprotein phosphatase activity
Biological process: peptidyl-threonine dephosphorylation; protein dephosphorylation; regulation of cell cycle
Cellular component: nucleoplasm; nucleus; cytoplasm; membrane
Genetic constraint (gnomAD): Loss-of-function variants: 11 observed, 55.81 expected, observed/expected ratio (o/e) 0.2, 90% interval 0.12 to 0.33. The upper end of that interval is the gene's LOEUF score, 0.33, which puts it in group 1 of 6, group 1 being the genes least tolerant of losing a copy. Missense variants: 389 observed, 680.12 expected, observed/expected ratio (o/e) 0.57, 90% interval 0.53 to 0.62. Synonymous variants: 243 observed, 257.08 expected, observed/expected ratio (o/e) 0.95, 90% interval 0.85 to 1.05.
Homologues: Orthologues: chimpanzee PPM1G (100% identical), macaque PPM1G (99% identical), rabbit PPM1G (98% identical), pig PPM1G (97% identical), dog PPM1G (97% identical), guinea pig PPM1G (95% identical), rat Ppm1g (94% identical), mouse Ppm1g (94% identical), tropical clawed frog ppm1g (73% identical), zebrafish ppm1g (66% identical). Paralogues in human: PPM1A (22% identical), PPM1B (22% identical), PPM1N (21% identical), PPM1E (19% identical), PPM1D (18% identical), PPM1F (18% identical), PPM1L (16% identical), PPM1K (16% identical), ILKAP (16% identical), PDP1 (15% identical), PDP2 (15% identical), PPM1H (14% identical), and 4 more.
Diseases named in the same sentence as PPM1G in open-access papers:
PPM1G is named in the same sentence as 33 diseases in open-access papers, as found by Europe PMC text mining. Sharing a sentence is not in itself a finding about the gene and the disease. The quoted sentences say what the papers report.
hepatocellular carcinoma (7 papers, 2021 to 2024). A malignant tumor that arises from hepatocytes. "We constructed the prognostic risk score for patients with hepatocellular carcinoma as follows: risk score = (0.3519) × PPM1G + (0.0637) × FKBP1A + (0.0673) × STAM + (0.0373) × MAD2L2 + (0.0031) × TBL1XR1 + (0.0172) × ANXA5." (PMID 38049741, 2023). "Moreover, although few members of the PPM family of proteins have been implicated in liver cirrhosis and hepatocellular carcinoma, the role of PPM1G in hepatic IRI has not been determined." (PMID 38372470, 2024). "Further experimentation revealed that in hepatocellular carcinoma, MYC/MAX and EP300 activate PPM1G which in turn dephosphorylates SRSF3, triggering the alternative splicing of genes related to cell cycle and transcriptional regulation." (PMID 37953273, 2023). "Recently, the significance of PPM1G in liver diseases has been elucidated, as PPM1G complexes with WWP2 promote liver fibrosis by overactivating the Notch3/HES1 pathway and contributing to the growth of hepatocellular carcinoma by modulating SRSF3 phosphorylation." (PMID 38372470, 2024). "We showed that the PPM1G, a protein phosphatase, regulated the phosphorylation of SRSF3 in hepatocellular carcinoma (HCC) and contributed to the proliferation, invasion, and metastasis of HCC." (PMID 34290239, 2021).
breast carcinoma (2 papers, 2021 to 2024). "PPM1G was reported to promote the dephosphorylation of α-catenin in breast cancer cell lines (MCF7 and MDA-MB-231), which was not reproduced in HEK293H cells." (PMID 39111820, 2024).
liver cancer (2 papers, 2021 to 2022). An epithelial or non-epithelial malignant neoplasm that arises from the liver. "We further verified our conclusion on liver cancer cell lines and liver cancer patient samples and found KNPA2 and PPM1G are high expressed in liver cancer cell lines and tissues from liver cancer patients." (PMID 36072981, 2022). "Therefore, we explored the relationship between PPM1G expression and liver cancer immune subtypes." (PMID 33952716, 2021).
liver fibrosis (2 papers, 2021 to 2024). "PPM1G plays a fundamental role in increasing liver fibrosis by negatively regulating the effect of WWP2 on Notch3 degradation." (PMID 33952716, 2021).
cervical cancer (1 paper, 2021). A primary or metastatic malignant neoplasm involving the cervix. "PPM1G and its coexpressed genes were enriched in cervical cancer, simian acquired immune deficiency syndrome, endometriosis, osteoarthritis, endometrial cancer, and hepatitis." (PMID 33952716, 2021).
glioblastoma (1 paper, 2021). The most malignant astrocytic tumor (WHO grade IV). "PPM1G is also involved in dephosphorylating the translation initiator 4E-BP1, thereby inhibiting the translation of its targets, such as Id1 in glioblastomas." (PMID 34290239, 2021).
gout (1 paper, 2024). A condition characterized by painful swelling of the joints, which is caused by deposition of urate crystals. "We validated a concordant direction of effect sizes of CTBP1, PPM1G, SEPT2, and KRTCAP3 for gout; SKIV2L for heart failure; and AAK1, MAPKAPK5-AS1, POLA2, RSG1, and WWP2 for hypertension." (PMID 38658550, 2024).
non-small cell lung carcinoma (1 paper, 2024). A group of at least three distinct histological types of lung cancer, including non-small cell squamous cell carcinoma, adenocarcinoma, and large cell carcinoma. "PPM1G but not PPM1G-YLmut overexpression promoted the dephosphorylation of eIF4E in A549 (a non-small-cell lung cancer [NSCLC]) cells and impaired ∼46% cell proliferation." (PMID 39111820, 2024).
Obesity (1 paper, 2023). Accumulation of substantial excess body fat. "It is also important to note that the novel EC proteins, APP, CAD, BRD2 (which is part of DKFZp313H139), CST3, GRN, PPM1G and ZC3H4, have all been reported to be positively associated with obesity or adiposity, whilst the novel EC protein SLC25A24 may even prevent obesity and promote leanness." (PMID 37760635, 2023).
papillary adenocarcinoma (1 paper, 2008). A morphologic variant of adenocarcinoma. "In contrast, those promoting Ca++ desensitization, such as the MLCPs (Ppm1a, Ppm1g, Pp2r2d, Ppp2r1a, Ppp1 catalytic subunit and Cdc42), were more highly expressed in the papillary adenocarcinoma tumors." (PMID 18811984, 2008).
viral infection (1 paper, 2022). "For example, viral infection can cleave K63-linked ubiquitin chains from STING by increasing MYSM1 levels or enhancing the recruitment of PPM1G to dephosphorylate STING." (PMID 36189363, 2022).
tumor (14 papers, 2014 to 2025). "To further explore the immune-related functions of PPM1G, we analyzed the association between PPM1G and the tumor microenvironment in TIMER." (PMID 33952716, 2021). "Therefore, we hypothesized that the expression of PPM1G might be linked to the tumor immune microenvironment in LIHC." (PMID 33952716, 2021). "We studied the tumor suppressor activity of the phosphatase PPM1G as it was reported that PPM1G dephosphorylates 4E-BP1." (PMID 39111820, 2024). "In previous studies, the biological significance of TBL1XR1, FKBP1A, and PPM1G in tumours has been well-documented." (PMID 38049741, 2023). "We subcutaneously transplanted the PPM1G knocked-down cells or vector-transfected cells into nude mice and observed the tumor volumes over time." (PMID 34290239, 2021). "PPM1G expression was significantly correlated with tumor purity (Spearman’s r=0.168, p=1.76E-03) and dominant immune cells." (PMID 33952716, 2021). "The tumor weight in the PPM1G knockdown group was also much less than that in the vector-transfected group." (PMID 34290239, 2021). "The influence of PPM1G expression in the tumor immune microenvironment was assessed via Tumor Immune Estimation Resource (TIMER)." (PMID 33952716, 2021). "The UALCAN website (which uses Liver Hepatocellular Carcinoma Project of The Cancer Genome Atlas (TCGA-LIHC) data) also showed that the PPM1G expression level in tumor tissues was significantly higher than that in normal tissues." (PMID 33952716, 2021). "The results suggest that PPM1G is correlated with the prognosis of LIHC patients and associated with the tumor immune microenvironment in LIHC." (PMID 33952716, 2021). "Our current studies are focused on unraveling the new functional substrates of PPM1G and further understanding its possible role as a tumor suppressor in human cancers." (PMID 25071155, 2014). "Similarly, DCAF13 and PPM1G have been shown to promote HCC progression by degrading tumor suppressors or modulating oncogenic signaling." (PMID 41355397, 2025). "PPM1G is found to be responsible for the dephosphorylation of pre-mRNA splicing factors, which take part in the formation of functional spliceosome and contribute to cell proliferation and tumor transformation." (PMID 38069262, 2023). "Meanwhile, the PPM1G knockdown resultant tumor growth suppression could be rescued by PPM1G overexpression." (PMID 34290239, 2021). "The mechanism of PPM1G in the tumor immune microenvironment deserves further exploration." (PMID 33952716, 2021). "Further studies showed that the knockdown of PPM1G inhibited tumor growth in vivo." (PMID 34290239, 2021). "Similarly, we retrieved the expression of PPM1G in the tumor samples and the normal samples in the TCGA-LIHC cohort, and the results in TCGA-LIHC supported the findings in our cohort." (PMID 34290239, 2021). "Together, these observations indicating knockdown PPM1G inhibited the tumor growth of HCC in vivo." (PMID 34290239, 2021). "Furthermore, if activation of key cellular programs is required to elicit critical responses to a DNA insult then it is possible that PPM1G would function as tumor suppressor." (PMID 27088130, 2016). "Since we determined that PPM1G positively regulates p73 levels and negatively regulates its counterpart ΔNp73 by controlling WWP2, it is tempting to speculate that PPM1G might act as a potential tumor suppressor." (PMID 25071155, 2014). "In terms of DNA methylation, SLC41A3, PPM1G, FAM83D, and UQCRH all showed significantly lower methylation levels in tumor tissues compared with normal tissues, with the most significant decrease observed for SLC41A3." (PMID 41355397, 2025). "By quantitative mass spectrometry analysis with anti-ACSL4 immunoprecipitates from lysates of HONE1 bulk tumor cells or TRCs, we identified kinases PCK2, PKM2 and PFKP, as well as phosphatase PPM1G, from the top 250 most enriched proteins in the precipitates." (PMID 38720107, 2024).
tumor (continued). "Then, we revealed regulatory factors and functional networks of PPM1G in LIHC and investigated its role in tumor immunity." (PMID 33952716, 2021). "PPM1G knockdown inhibits HCC cell growth, invasion, and tumor growth in vivo." (PMID 35799605, 2022). "EZH2, TUBG1, and PPM1G are related to the ferroptosis gene, FANCD2, and may be involved in tumor biological behaviors mediated by ferroptosis." (PMID 36686830, 2022).
cancer (8 papers, 2014 to 2025). A tumor composed of atypical neoplastic, often pleomorphic cells that invade other tissues. "Many studies have focussed on mTORC1 regulation of translation on the control of cell growth, particularly in cancer settings, and previous work has shown that endogenous PP2Cγ/ PPM1G contributes to 4E-BP1 dephosphorylation in 293 and HCT116 cells." (PMID 40548551, 2025). "We analyzed the PPM1G expression patterns in the results of various cancer studies from the data of The Cancer Genome Atlas (TCGA) and Gene Expression Omnibus (GEO)." (PMID 33952716, 2021). "Gene Expression Profiling Interactive Analysis (GEPIA) (which uses TCGA data) showed that compared with that in normal tissues, the PPM1G mRNA levels were significantly higher in 11 types of cancer tissues." (PMID 33952716, 2021). "Therefore, PPM1G dysfunction may induce cancer progression by affecting pre-mRNA splicing, making it a hot spot in current research." (PMID 36531219, 2022). "The pan-cancer analysis results suggest that the eight hub genes (TXNRD1, TUBG1, SF3B4, PPM1G, PIGU, NDRG1, GRPEL2, and EZH2) were differentially expressed in gastrointestinal tumors." (PMID 36686830, 2022). "The results of previous studies have confirmed that SLC41A3, SEC61A1, LRP4, PPM1G, and HSP90AA1 play important roles in cancer progression." (PMID 35799605, 2022). "Therefore, dysfunction of PPM1G may induce cancer progression by affecting pre-mRNA splicing." (PMID 33952716, 2021).
PPM1G also shares sentences with these, for which no sentence is quoted: alcohol (2 papers); bladder cancer (1); cholangiocarcinoma (1); colon cancer (1); endometrial cancer (1); endometriosis (1); gastrointestinal tumors (1); glioma (1); heart failure (1); Hepatitis (1); Hypertension (1); leukemia (1); liver cirrhosis (1); liver diseases (1); lung carcinoma (1); osteoarthritis (1); ovarian carcinoma (1); pancreatic cancer (1); skin cancer (1); testicular cancer (1).